LINC00470 (long independently transcribed non-coding RNA 470)
Synonyms: formerly C18orf2
Gene: Long non-coding RNA gene on chromosome 18 (1,254,383 to 1,408,344, reverse strand). Ensembl gene ENSG00000132204.
Diseases named in the same sentence as LINC00470 in open-access papers:
LINC00470 is named in the same sentence as 16 diseases in open-access papers, as found by Europe PMC text mining. Sharing a sentence is not in itself a finding about the gene and the disease. The quoted sentences say what the papers report.
gastric cancer (8 papers, 2020 to 2024). A primary or metastatic malignant neoplasm involving the stomach. "In agreement with our findings, the LINC00470 expression was noticeably enhanced in gastric cancer tissues and cell lines, which was likewise associated with poor prognosis, distant metastasis, and tumor-node-metastasis stage." (PMID 34249684, 2021). "Meanwhile, they demonstrated that LINC00470 induced the degradation of PTEM mRNA to promote gastric cancer proliferation, migration, and invasion." (PMID 33875645, 2021). "There is wide recognition that LINC00470 is a critical participant in the tumorigenesis of cancers such as gastric cancer and glioblastoma, but its possible effects on EC progression remain to be explored." (PMID 34249684, 2021). "In gastric cancer, LINC00470 was also highly expressed and facilitated the malignant behavior of gastric cancer cells through degrading PTEN mRNA28." (PMID 33875645, 2021). "Interestingly, miR-4429 inhibited the expression of METTL3, resulting in down-regulation of SEC62 expression, thereby preventing the progression of gastric cancer; LncRNA LINC00470 is significantly up-regulated in gastric cancer tissues and cell lines." (PMID 35070987, 2021). "For example, LINC00470 inhibits the PTEN stability by binding to METTL3 and promotes gastric cancer progression." (PMID 36032659, 2022). "Overexpression of LINC00470 was correlated with TNM stage and distant metastasis status of gastric cancer." (PMID 33834618, 2021). "In gastric cancer, studies have shown that the degradation of PTEN mRNA mediated by LINC00470-METTL3 depends on the m6A read protein YTHDF2-dependent pathway to promote the malignant behavior of gastric cancer cells." (PMID 33505426, 2020). "LINC00470 has been reported to be highly expressed in gastric cancer and glioblastoma, but has not been proven to be related to EC." (PMID 34249684, 2021). "For example, LINC00470 interacts with METTL3 to promote PTEN mRNA degradation, promoting gastric cancer (GC) progression." (PMID 38166703, 2024).
glioma (8 papers, 2020 to 2024). A benign or malignant brain and spinal cord tumor that arises from glial cells (astrocytes, oligodendrocytes, ependymal cells). "Our previous studies have demonstrated that elevated expression levels of LINC00470 were associated with poor prognosis in glioma patients and promoted the glioma growth in an intracranial transplantation mouse model by activating the AKT signalling pathway." (PMID 32916774, 2020). "The lncRNA LINC00470, overexpressed in several tumors, including gliomas, was pathologically overrepresented in GDEVs and was associated with disease severity and postoperative survival time of glioma patients." (PMID 38020906, 2023). "Also, the expression of exosomal LINC00470 positively correlated with the clinicopathological characteristics and negatively associated with postoperative survival of glioma patients, supporting its role as a prognosis biomarker for glioma patients." (PMID 33663509, 2021). "In addition, LINC00470 was overexpressed in GDEs and associated with disease severity and postoperative survival time of glioma patients." (PMID 34887381, 2021). "The coexpressed genes of LINC00470 in glioma data of The Cancer Genome Atlas were further searched and intersected with the highly expressed genes in the GSE50161 microarray and the transcription factor data downloaded from the Cistrome database." (PMID 36987665, 2023). "According to the average expression of LINC00470, glioma patients were classified into LINC00470 high expression group (n = 26) and LINC00470 low expression group (n = 19)." (PMID 33663509, 2021). "LINC00470 overexpressed in GBM-exo and associated with disease severity and postoperative survival time of glioma patients." (PMID 33663509, 2021). "LINC00470 in GBM-exo can bind to miR-580-3p in glioma cells to regulate WEE1 expression and activate the PI3K/AKT/mTOR pathway, thereby inhibiting autophagy and enhancing the proliferation of glioma cells." (PMID 33663509, 2021). "Herein, we identified that exosomal LINC00470 as an oncogene in glioma that promoted the proliferation of glioma cells by inhibiting glioma cell autophagy." (PMID 33663509, 2021). "Taken together, these findings revealed a novel molecular mechanism of LINC00470 regulating autophagy and proliferation of glioma cells and provided a potential therapeutic target for glioma treatment." (PMID 33663509, 2021). "By detecting the LINC00470 expression in serum of glioma patients, we found that LINC00470 overexpressed in exosomes from serum of glioma patients." (PMID 33663509, 2021). "The expression of LINC00470 in glioma patients were measured and recorded to calculate the average expression of LINC00470 in glioma patients." (PMID 33663509, 2021). "Expression of LINC00470 in exosomes was analyzed with the clinicopathological characteristics of glioma patients." (PMID 33663509, 2021). "We subsequently identified the effect of exosomal LINC00470 in glioma patient serum on the growth of primary glioma in nude mice." (PMID 33663509, 2021). "Collectively, these results indicated that exosomes isolated from serum of glioma patients enhanced the tumorigenesis of U251 cells in nude mice, while LINC00470 knockdown inhibited the growth of xenograft tumor." (PMID 33663509, 2021). "As a dominant regulator of glioma cell autophagy, LINC00470 promoted the expression of ELFN2 through sponge of miR-101 to distract glioma cell autophagy." (PMID 33663509, 2021). "We found that LINC00470 expression was the lowest in serum exosomes from HCs, and glioma patients in grade III–IV had the highest LINC00470 expression (P < 0.05)." (PMID 33663509, 2021). "In the present study, we further confirmed that LINC00470 was highly expressed in gliomas and promoted glioma cell proliferation and invasion, and attenuated TMZ chemosensitivity." (PMID 32916774, 2020). "We found that the expression of LINC00470 in glioma tissues was significantly up‐regulated relative to normal brain tissues." (PMID 32916774, 2020).
glioma (continued). "Functional studies have shown that LINC00470 promotes proliferation and invasion, and attenuates chemosensitivity of glioma cells, while miR‐134 exerts the opposite effect." (PMID 32916774, 2020). "In order to explore the biological role of LINC00470 in glioma cells, an LINC00470 overexpression plasmid was transfected into cell lines U87 and U251." (PMID 32916774, 2020). "Although we identified the role of LINC00470 and miR‐134 in glioma and established the LINC00470/miR‐134/MYC/ABCC1 axis, certain limitations out of our study remain and should be improved upon in the future." (PMID 32916774, 2020). "In this study, we analysed the expression of LINC00470 in 32 glioma tissues and 7 normal brain tissues from the Department of Neurosurgery, Xiangya Hospital, China, by RT‐qPCR." (PMID 32916774, 2020). "Meanwhile, compared with normal brain tissue cell line HEB, the expression levels of LINC00470 in glioma cell lines U87 and U251 were also up‐regulated." (PMID 32916774, 2020). "After overexpression of LINC00470 and the intervention of Rapa, glioma cell autophagy was strengthened while proliferation was impeded, suggesting that LINC00470 mediated glioma cell proliferation through modulating glioma cell autophagy." (PMID 33663509, 2021). "Consistently, GBM-exo, LINC00470 overexpression or miR-580-3p knockdown could activate PI3K/AKT/mTOR signaling pathway, supporting the regulatory role of LINC00470 on PI3K/AKT/mTOR signaling pathway in glioma cells." (PMID 33663509, 2021). "But how PI3K/AKT/mTOR signaling pathway was activated and whether LINC00470 can regulate PI3K/AKT/mTOR signaling pathway in glioma are potential uncertainties for a better understanding of glioma." (PMID 33663509, 2021). "LINC00470 in GDE could competitively bind to miR-580-3p in glioma cells to modify WEE1 expression and activate the PI3K/AKT/mTOR pathway, thus suppressing autophagy and strengthening the proliferation of glioma cells." (PMID 34887381, 2021). "We extracted exosomes from the serum of glioma patients and measured the expression of LINC00470 in the exosomes to further analyze whether the expression of LINC00470 correlated with the clinicopathological characteristics of glioma patients." (PMID 33663509, 2021). "Previous studies have proved overexpression of LINC00470 in glioma." (PMID 33663509, 2021). "Nevertheless, how LINC00470 regulates cell autophagy in glioma remains to be determined." (PMID 33663509, 2021). "To clarify whether the tumour‐promoting effect of LINC00470 in glioma cells can be mediated by miR‐134, we performed rescue experiments." (PMID 32916774, 2020). "In addition, expression of miR‐134 was down‐regulated when we overexpressed LINC00470 in glioma cells, whereas expression of LINC00470 was down‐regulated when we overexpressed miR‐134." (PMID 32916774, 2020). "To determine whether LINC00470 and miR‐134 also exhibit similar interactions in gliomas, we first predicted the binding site of LINC00470 and miR‐134 using bioinformatics analysis." (PMID 32916774, 2020). "Our results provide a new understanding of the role and mechanism of the LINC00470/miR‐134/MYC/ABCC1 axis in glioma, which may contribute to the development of novel therapeutic targets and improve the chemosensitivity of glioma." (PMID 32916774, 2020). "Therefore, we hypothesized that exosomal LINC00470 modulated glioma cell proliferation through regulating glioma cell autophagy." (PMID 33663509, 2021). "However, the role and mechanism of LINC00470 in glioma must be further elucidated; in particular, it remains unclear whether LINC00470 affects the chemosensitivity of glioma." (PMID 32916774, 2020). "LINC00470 inhibits the ubiquitination of HK1, the first key enzyme in the glycolysis pathway, thereby affecting glycolysis, and inhibiting cell autophagy in gliomas." (PMID 36180956, 2022).
glioma (continued). "LINC00470 in GBM- exosome can bind to miR-580-3p in glioma cells and stimulate the PI3K/AKT/mTOR pathway, impeding autophagy and promoting glioma cell proliferation." (PMID 37305396, 2021). "More specifically, we identified LINC00470 can bind to miR-580-3p to regulate WEE1 and thereby regulate PI3K/AKT/mTOR pathway, ultimately mediating cell autophagy in glioma." (PMID 33663509, 2021). "In this study, we found elevated expression levels of LINC00470 and MYC in glioma tissues and cells and decreased expression of microRNA‐134 (miR‐134)." (PMID 32916774, 2020). "We concluded that LINC00470 promoted the expression of MYC and ABCC1 by suppressing miR‐134, thus promoting glioma cell proliferation and invasion, and attenuating TMZ chemosensitivity." (PMID 32916774, 2020). "Meanwhile, we found that miR‐134 rescued LINC00470‐induced cell proliferation, invasion and reduction of TMZ chemosensitivity, which indicated that the effect of LINC00470 on glioma was mediated by miR‐134." (PMID 32916774, 2020). "In our previous studies, we found that LINC00470 activated the AKT signalling pathway and promoted the tumour growth of intracranial transplantation mouse model with glioma." (PMID 32916774, 2020). "Our study clarified the new mechanism by which LINC00470 acts as a ceRNA to sponge miR‐134, thereby regulating downstream molecules such as MYC and ABCC1 to maintain the malignant phenotype of glioma." (PMID 32916774, 2020). "The results demonstrated that LINC00470 in serum exosomes from glioma patients, through competing with WEE1 to bind miR-580-3p, could augment proliferation and impair the autophagy of glioma cells via activating PI3K/AKT/mTOR signaling pathway." (PMID 33663509, 2021). "Thus, we identified the LINC00470/miR‐134/MYC/ABCC1 axis and illuminated its biological role and mechanism in glioma." (PMID 32916774, 2020). "Furthermore, we determined that LINC00470 indirectly regulates the expression of MYC by sponging miR‐134, thus regulating the malignant phenotype and TMZ sensitivity of glioma cells." (PMID 32916774, 2020). "That is, LINC00470, miR‐134, MYC and ABCC1 can form a new regulatory axis in gliomas." (PMID 32916774, 2020). "In order to clarify whether MYC was involved in the tumour‐promoting role of LINC00470, we analysed the expression level of MYC in LINC00470‐overexpressing glioma cells." (PMID 32916774, 2020). "As expected, sh-LINC00470 increased the number of acidic autophagosomes and the expression levels of LC3-II/LC3-I and Beclin1, while decreased the expression of p62, corroborating that it was LINC00470 that suppressed autophagy and potentiated proliferation in glioma cells." (PMID 33663509, 2021). "In this study, we demonstrated that LINC00470 secreted by serum exosomes from glioma patients can bind miR-580-3p to regulate WEE1 expression and activate PI3K/AKT/mTOR signaling pathway, thus inhibiting glioma cell autophagy and promoting glioma cell proliferation." (PMID 33663509, 2021). "In addition, Pearson's chi‐squared test revealed a significant negative correlation between the expression levels of LINC00470 and miR‐134 in thirty‐two glioma tissues." (PMID 32916774, 2020).
glioblastoma (7 papers, 2020 to 2023). The most malignant astrocytic tumor (WHO grade IV). "Bioinformatics analysis was conducted to predict the potential mechanism of LINC00470 in glioblastoma, which was validated by dual‐luciferase reporter, RIP, ChIP, and RNA pull‐down assays." (PMID 36987665, 2023). "Conclusively, temozolomide repressed glioblastoma progression by repressing the LINC00470/EGR2/SOX4 axis." (PMID 36987665, 2023). "A prior study indicated that LINC00470 was highly expressed in the serum exosomes of glioblastoma patients." (PMID 36987665, 2023). "In this study, LINC00470 knockdown or temozolomide treatment both diminished SOX4 expression in glioblastoma cells." (PMID 36987665, 2023). "Specifically, temozolomide treatment restricted cell invasion, migration, and angiogenesis but facilitated cell autophagy and apoptosis in glioblastoma via the inactivation of the LINC00470/EGR2/SOX4 axis." (PMID 36987665, 2023). "Intriguingly, high LINC00470 expression was also exhibited in brain tissues from patients with glioblastoma in our study." (PMID 36987665, 2023). "This study also manifested that the protective effect of temozolomide treatment on glioblastoma was further enhanced by LINC00470 knockdown but abolished by LINC00470 overexpression." (PMID 36987665, 2023). "This study illustrated that temozolomide suppressed cell proliferation, migration, invasion, and angiogenesis, but accelerated cell apoptosis, autophagy in glioblastoma, as well as restricted tumor growth in vivo, by disrupting the LINC00470/EGR2/SOX4 axis." (PMID 36987665, 2023). "Findings in this study also revealed that temozolomide treatment prominently diminished LINC00470 expression in glioblastoma cells." (PMID 36987665, 2023). "LINC00470 plays an oncogenic role in glioblastoma multiforme (GBM)-derived exosome by binding to miR-580-3p, regulating the levels of WEE1 and activating the PI3K/AKT/mTOR pathway." (PMID 36338993, 2022). "Recently, LINC00470 was found highly expressed in the glioblastoma tissues and cells, which activated AKT signaling and promoted the expression of ELFN2 to inhibit cell autophagy and induce tumorigenesis." (PMID 33875645, 2021). "Previously, LINC00470 was found to regulate glioblastoma development through mediating cell autophagy." (PMID 33875645, 2021). "Collectively, temozolomide might repress cell proliferation, migration, invasion, and angiogenesis in glioblastoma through the disruption of the LINC00470/EGR2/SOX4 axis." (PMID 36987665, 2023). "Temozolomide repressed glioblastoma progression by repressing the LINC00470/EGR2/SOX4 axis." (PMID 36987665, 2023). "Overall, temozolomide treatment might block the LINC00470/EGR2/SOX4 axis to constrain glioblastoma growth in vivo." (PMID 36987665, 2023). "In addition, our data also revealed that EGR2 and LINC00470 expression decreased with the elevation of temozolomide concentration in glioblastoma cells." (PMID 36987665, 2023). "Altogether, temozolomide treatment might also facilitate apoptosis and autophagy of glioblastoma cells in vivo and in vitro by blocking the LINC00470/EGR2/SOX4 axis." (PMID 36987665, 2023). "Moreover, EGR2 overexpression nullified the inhibitory effects of temozolomide treatment and LINC00470 knockdown on glioblastoma cell malignant behaviors." (PMID 36987665, 2023). "Taken together, temozolomide may restrain the malignant behaviors of glioblastoma by dampening the LINC00470/EGR2/SOX4 axis." (PMID 36987665, 2023). "This study further ascertained whether the regulation of temozolomide on cell apoptosis and autophagy in glioblastoma also involved the LINC00470/EGR2/SOX4 axis." (PMID 36987665, 2023). "Collectively, temozolomide might affect glioblastoma survival by suppressing LINC00470‐modulated EGR2." (PMID 36987665, 2023). "Bioinformatics analysis and experiments initially revealed that LINC00470 might exhibit regulatory effects in glioblastoma via EGR2 during temozolomide treatment." (PMID 36987665, 2023).
glioblastoma (continued). "As reported, LINC00470 is a new AKT activator that mediates glioblastoma cell autophagy." (PMID 36275661, 2022). "Additionally, LINC00470 plays a vital role in the tumorigenesis of glioblastoma and its high expression correlates with poor prognosis of patients with glioblastoma." (PMID 34249684, 2021). "Temozolomide restrained glioblastoma growth and angiogenesis in vivo, while LINC00470 or SOX4 overexpression nullified but LINC00470 knockdown further facilitated these trends." (PMID 36987665, 2023). "LINC00470 and EGR2 mRNA expression gradually decreased with increasing concentrations of temozolomide in glioblastoma cells, and SOX4 expression was reduced in cells by temozolomide and LINC00470 knockdown." (PMID 36987665, 2023). "This study is dedicated to delve into the impact of the relationship between temozolomide and the LINC00470/EGR2/SOX4 axis on glioblastoma progression, thus presenting a fresh theoretical basis for the treatment of glioblastoma with temozolomide." (PMID 36987665, 2023). "LINC00470, known as C18orf2, also activates AKT signaling, inhibits cell autophagy and promotes glioblastoma cell tumorigenesis and poor patient prognosis." (PMID 33239065, 2020). "LINC00470 and EGR2 were highly expressed in brain tissues of glioblastoma patients." (PMID 36987665, 2023).